ACE (angiotensin I converting enzyme)
Diseases named in the same sentence as ACE in open-access papers (continued):
Sharing a sentence is not in itself a finding about the gene and the disease.
Hypertension (continued). "However, when considering each particular NCD, BM possessed high potential to control T2DM occurrence through inhibition of α-amylase and α-glucosidase, while BM and DM showed potential to ameliorate hypertension through ACE inhibition." (PMID 38066118, 2023). "Regarding the effects of ACE inhibitors, it is shown that certain medications can also slow down and even reverse reactive interstitial fibrosis, which is important in patients with hypertension." (PMID 38138252, 2023). "However, compared to healthy controls, ACE genotype II was less common in patients with hypertension." (PMID 37034069, 2023). "In this function, ACE inhibition is beneficial to health through controlling hypertension." (PMID 36834822, 2023). "Natural marine ACE inhibitors are being studied as alternatives to synthetic drugs to avoid several serious side effects and hold a significant potential to become new therapeutic options for the treatment of hypertension." (PMID 36976242, 2023). "Many marine natural compounds, including bioactive molecules, chito-oligosaccharide derivatives (COS), and phlorotannins, were obtained from marine species and are potential leads for ACE inhibitors and evolved as nutraceutical medicinal compounds for the treatment of hypertension." (PMID 36976242, 2023). "Interestingly, our patient developed hypertension during her hospitalization and was initiated on ACE inhibitors for blood pressure management, in addition to Apixaban for anticoagulation." (PMID 37038580, 2023). "ACE inhibitors are one of the first-line treatments for hypertension and congestive heart failure." (PMID 36834822, 2023). "Angiotensin-converting enzyme (ACE) inhibitors are a common therapy for treating hypertension." (PMID 37759668, 2023). "Therefore, inhibition or inactivation of ACE is recognized as a straightforward approach to relieving hypertension." (PMID 37242257, 2023). "Therefore, it becomes very important to control and inhibit hypertension and ACE using natural compounds such as phytocompounds like saponins, terpenes, and isoflavonoids." (PMID 37324400, 2023). "ACE is a key enzyme in the RAAS which helps in the regulation of hypertension." (PMID 37324400, 2023). "Angiotensin-converting enzyme (ACE) inhibitors or angiotensin II receptor blockers (ARBs) are recommended as first-line drugs for hypertension with diabetic nephropathy owing to their renoprotective effect; however, their effect beyond lowering blood pressure (BP) has not been confirmed." (PMID 36100672, 2023). "In some ways, diuretics may replace β-blockers and angiotensin-converting enzyme (ACE) inhibitors in the treatment of hypertension." (PMID 36771707, 2023). "It was also recently shown than a 6-week antihypertensive treatment with the sulfhydryl-donating angiotensin converting enzyme (ACE) inhibitor Captopril improved cutaneous microvascular endothelium-dependent vasodilation in middle-aged adults with hypertension." (PMID 37373103, 2023). "Reversing the effects of the RAAS system through the use of medications such as ACE inhibitors, ARBs, and MRAs has proven effective in lowering blood pressure and enhancing cardiovascular outcomes in patients with hypertension, including those with resistant hypertension." (PMID 37416924, 2023). "ACE inhibitors are indicated for uncomplicated hypertension, as well as for hypertension and concomitant CAD (including post-myocardial infarction), chronic kidney disease (CKD), type 2 diabetes, heart failure with reduced ejection fraction, or atrial fibrillation." (PMID 34533690, 2023). "Omapatrilat was developed as a dual neutral endopeptidase (NEP) and angiotensin-converting enzyme (ACE) inhibitor that has been experimentally assessed as a hypertension treatment, while tenatoprazole was a clinical candidate for peptic ulcer and reflux functioning as a proton pump inhibitor." (PMID 37244126, 2023).
Hypertension (continued). "We mainly identified that compared to non‐diabetic patients with COVID‐19, patients with DM were older, more likely to have hypertension, a higher blood glucose on admission, be taking ACE inhibitors or ARBs and have a higher platelet count but lower lymphocytes, AST and ALP." (PMID 36426913, 2023). "Drugs that inhibit ACE are common for the treatment of hypertension." (PMID 38004148, 2023). "Genetic polymorphisms in ACE and ACE2 genes are involved in the RAS regulation of blood pressure and their activity may confer susceptibility to hypertension." (PMID 37667339, 2023). "ACE-inhibitors are a class of medication used to treat hypertension and cardiovascular conditions." (PMID 38162307, 2023). "Advanced studies with a considerable sample size may be needed to utilize the ACE genotype as a biomarker for the early detection of hypertension-related complications." (PMID 37200278, 2023). "A number of RAAS gene polymorphisms, including those in the aldosterone synthase (CYP11B2), angiotensinogen (AGT), angiotensin II type 1 receptor (AT1R), and angiotensin-converting enzyme (ACE) genes, have been found to be strongly linked to hypertension and ischemic stroke." (PMID 37034069, 2023). "Again, several antioxidants possess ACE-inhibiting activities and aid in reducing hypertension." (PMID 37342546, 2023). "In patients with high blood pressure treated with certain diuretics, i.e., thiazide diuretics, ACE-inhibitors, and angiotensin-II receptor antagonists, or undergoing low sodium diet, serum levels of lithium might increase up to toxic concentrations." (PMID 38057894, 2023). "Thus, synthetic ACE inhibitors have been used as a first-line pharmaceutical drug for hypertension therapy." (PMID 37446561, 2023). "ARBs are a common choice for the treatment of high blood pressure, as well as for the prevention of renal problems in sufferers with diabetes, and are the preferred medication in patients who experience cough with the use of ACE inhibitors." (PMID 37299008, 2023). "Therefore, the current study is the first one to be done in the Ethiopian population and assessed the effect of the ACE genotype on the anthropometric measures and biochemical features of essential hypertension." (PMID 37200278, 2023). "Thus, pear pomace powder has the potential to provide dietary support as an ACE inhibitor effective in the treatment of high blood pressure, heart failure, type 2 diabetes and diabetic nephropathy." (PMID 38231877, 2023). "Individuals with hypertension have been shown to have reduced levels of circulating ACE2 with the adverse consequence of increased concentration of the vasoconstricting molecule Angiotensin II due to activation of ACE." (PMID 36099266, 2022). "The angiotensin-I-converting enzyme (ACE) can convert angiotensin I (Ang I) to Ang II for inactivating the vasodilator bradykinin, and ACE inhibitory (ACEi) activity is a noticeable method for mediating systemic hypertension." (PMID 35495901, 2022). "The first difference may be explained by ACE inhibitors and ARBs being the preferred agents in the management of hypertension in patients with diabetes and because of their beneficial effects on albuminuria in diabetic nephropathy." (PMID 36068573, 2022). "Additionally, this study found that male gender, baseline glucose level, hypertension, and thiazide use showed an increased risk of NODM, whereas angiotensin-converting enzyme (ACE) inhibitor or angiotensin II receptor blocker (ARB) showed a decreased risk." (PMID 36554779, 2022). "The large number of drugs prescribed to patients with hypertension and diabetes mellitus can be attributed to beta-blockers, ACE inhibitors, hypolipidemic agents, calcium channel blockers, insulin, and anticoagulants to decrease the risk of various complications." (PMID 35208508, 2022).
Hypertension (continued). "Another consideration is cardiovascular outcomes which have been flagged from a recent meta-analysis comparing the effect of ACE inhibitors or ARBs against other antihypertensives such as calcium channel blockers amongst Black people with hypertension with 4-to-6-year follow-up." (PMID 34508156, 2022). "IONIS-AGT-LRx (80 mg weekly via subcutaneous injection) has been evaluated in 2 double-blind, placebo-controlled trials in subjects with hypertension, either as monotherapy (25 patients) or as an add-on on top of ACE inhibitors/ARBs (26 patients) versus placebo for up to 2 months." (PMID 35904033, 2022). "Although hypertension is more prominent among black people, there is data demonstrating that some antihypertensive drugs, such as ACE inhibitors and ARBs, are less effective and have increased consequences when given to black people than to individuals of other races." (PMID 36430371, 2022). "However, in many cases, patients receive ACE inhibitors (ACEIs) or angiotensin receptor blockers (ARBs) in the context of hypertension and heart or kidney disease." (PMID 36291638, 2022). "Inhibition of ACE (ACE-I) is considered as one of the main strategies to reduce hypertension." (PMID 36010429, 2022). "Despite being ACE inhibitors, therapies for hypertension must be maintained." (PMID 37361869, 2022). "We are unaware of any single US FDA-approved drug that can address all three conditions, although inexpensive monotherapies are available for treating hypertension (e.g., ACE inhibitors and beta blockers), hyperlipidemia (e.g., statins), and type II diabetes (e.g., metformin)." (PMID 35260150, 2022). "It is of note that hypertension exacerbates airway hyperinflammation in patients with COVID-19 and that treatment with ACE inhibitors might ameliorate airway hyperinflammation." (PMID 36119050, 2022). "These natural ACE inhibitory bioactive peptides are highly desired for the development of functional foods, nutraceuticals and pharmaceuticals for the prevention and treatment of hypertension." (PMID 35571042, 2022). "Hence, the methanol extract has an activity against hypertension that is comparable to the ACE inhibition activity achieved with the standard drug captopril, while n-hexane has a 35% inhibitory effect that is least comparable to the reference standard." (PMID 36249822, 2022). "As a widely used compound, curcumin might be used to treat hypertension by modulating the interaction of ACE with bradykinin system in VSMCs dependent on NF-κB and AP-1 signaling." (PMID 35530510, 2022). "Therefore, ACE inhibitors are useful in treating hypertension, many of which are derived from foods such as mushrooms." (PMID 36143487, 2022). "Interaction between OSA and the ACE gene I/D polymorphism was significantly associated with presence of hypertension among Swedish patients but not in the Turkish cohort." (PMID 36246876, 2022). "In addition, in a cardiac model, the formulation reduced the activity of the hypertension-related angiotensin-converting enzyme (ACE)." (PMID 35453303, 2022). "Moreover, the treatment with ACE inhibitors and ARBs favored the reduction of C-reactive protein and procalcitonin levels in patients with COVID-19 and hypertension." (PMID 36187294, 2022). "Furthermore, angiotensin-converting enzyme (ACE) inhibitors are the first choice in treating hypertension to maintain a blood pressure of less than 130/80 mmHg." (PMID 35242470, 2022). "Concerning antihypertensives, the main drugs used in the treatment of hypertension are as angiotensin converting enzyme (ACE) inhibitors and angiotensin-receptor blockers (ARBs), two different class of medications that lower blood pressure targeting the renin-angiotensin system (RAAS)." (PMID 35628307, 2022).
Hypertension (continued). "Furthermore, during hypertension or diabetes, a deficiency of ACE2 and increased ACE/ACE2 ratio have been noted, and cardioprotective treatments with ACE inhibitors and Ang-II receptor blockers exert their effects partly by increasing ACE2 levels." (PMID 35586646, 2022). "The importance of this system in the pathogenesis of hypertension and other cardiovascular diseases is exemplified by the therapeutic success of angiotensin converting enzyme (ACE) inhibitors and angiotensin II type I receptor (AT1R) antagonists in treating these diseases." (PMID 35086455, 2022). "ACE inhibition is considered to be an effective therapeutic strategy to treat hypertension." (PMID 36557925, 2022). "Pharmaceutical manufacturers have commercialised many ACE inhibitors to lower angiotensin II concentrations for the treatment of hypertension; however, these drugs possess adverse side effects, emphasising the need for developing natural food-derived inhibitors with fewer undesirable side effects." (PMID 36140958, 2022). "Therefore, other classes of antihypertensives with good safety and efficacy data (such as ACE-inhibitors, calcium-channel blockers or others) should become the preferred first-line agents in the treatment of hypertension." (PMID 35235571, 2022). "Today, ACE inhibitors are widely used to manage hypertension." (PMID 36432059, 2022). "Given the evidence for its efficacy in this study, its clinical uses for hypertension, renal and liver disease, and the fact that other ACE inhibitors have extended rodent lifespan, follow‐up studies are warranted to establish replicability and if, replicable, optimal dosage." (PMID 36179270, 2022). "There was considerable degree of sympathovagal imbalance (increased LF-HF ratio) in these subjects, despite them receiving the calcium channel blockers and ACE inhibitors for the treatment of hypertension that are known to decrease sympathetic discharge and improve autonomic balance." (PMID 36085061, 2022). "Potentially, early identification and treatment of hypertension with ACE inhibition may prevent the need for PICU admission and decrease the risk of hypertension-related complications." (PMID 35205701, 2022). "As a result, the ACE gene is a good candidate for studying the pathophysiology of hypertension." (PMID 36011305, 2022). "Moreover, ET-1 stimulates endothelial angiotensin-converting enzyme (ACE) activity and secretion of aldosterone participating in hypertension development." (PMID 35953533, 2022). "ACE inhibitors commonly treat hypertension, heart failure, and myocardial infarction." (PMID 36187294, 2022). "Most frequently, individuals with hypertension used ACE-inhibitors/ARBs (72.5%)." (PMID 36555930, 2022). "Thus, the Angiotensin-converting enzyme (ACE)-Angiotensin II (Ang II)-Angiotensin II type 1 receptor (AT1R) axis seems to be involved in worsening of hypertension, atherosclerosis and thrombogenesis." (PMID 35054468, 2022). "According to the authors, the control of hypertension by HS consumption may be related to its angiotensin-converting enzyme (ACE) inhibitory effect and serum sodium balance." (PMID 35455462, 2022). "Recent studies have shown that hypertension can be treated by inhibiting ACE." (PMID 36176638, 2022). "Although the widely utilized synthetic ACE inhibitors, such as captopril, lisinopril, and enalaprilat, are currently the mainstay in the treatment for hypertension, they can also produce a serious variety of side effects such as dry cough, renal dysfunction, and angioedema." (PMID 35159478, 2022). "Data regarding the participation of the RAAS in hypertension pathophysiology in the SHR are driven mainly by the impact of targeted inhibition of the presumably deleterious classical ACE/Ang II/AT1R pathway or by activation of the supposedly beneficial alternative ACE2/Ang 1-7/MasR pathway." (PMID 36009391, 2022). "ACE-inhibitory peptides demonstrated great therapeutic potential to prevent hypertension." (PMID 36499176, 2022).
Hypertension (continued). "ACE inhibitors or ARBs for treatment of hypertension had a negative association with hepatic fibrosis (OR, 0.37; 95% CI, 0.21–0.65; p = 0.001)." (PMID 36230773, 2022). "This suggests that treatment of hypertension with ACE-inhibitors or ARBs may have a role on survival by affecting disease progression at late stages, not on early stages of the disease progress." (PMID 34921656, 2022). "The most active peptide, i.e., MVPYPQR had ACE-inhibitory IC50 values of 30 μM in addition to antioxidant activity (8933.05 μM TE mg−1 peptide) Inhibition of ACE activity is considered an active therapy to reduce hypertension concerns." (PMID 35893855, 2022). "Inhibition of ACE activity is considered to be an effective treatment for hypertension." (PMID 35159478, 2022). "In fact, that study considered oyster protein to be the best natural source of ACE-inhibitory peptides, such that those peptides could be incorporated into functional foods for hypertension." (PMID 35733526, 2022). "It is shown that ACE enzyme is involved in RAAS regulation and ACE gene I/D polymorphism may play a role in hypertension development." (PMID 36246876, 2022). "Because of the higher prevalence of coronary artery disease and hypertension in the high PP group, the patients in the high PP group more frequently took beta blockers, ACE inhibitors/ Angiotensin II receptor blockers, and Calcium channel blockers before admission and after discharge." (PMID 34882954, 2022). "Seven Ob‐T2D participants had a known diagnosis of hypertension and were prescribed anti‐hypertensives including ACE inhibitors such as ramipril, calcium channel blockers such as amlodipine, and one participant was prescribed the thiazide diuretic, bendroflumethiazide." (PMID 35964329, 2022). "Angiotensin-I-converting enzyme (ACE) inhibitors are used extensively to control hypertension." (PMID 36557925, 2022). "Therefore, inhibiting the enzyme activity of Renin and ACE is one of the treatments for hypertension." (PMID 36825069, 2022). "Moreover, antihypertensive peptides, useful in the treatment of hypertension disease due to the ability to inhibit the Angiotensin-I-Converting Enzyme (ACE), have been discovered in food proteins/peptides and are known as ACE inhibitory peptides." (PMID 35202112, 2022). "In summary, these reports have shown that phenolics may regulate RAS by inhibiting renin and/or ACE and have a beneficial effect on the treatment of hypertension." (PMID 35424726, 2022). "Moreover, several ACE inhibitory peptides able to prevent or reduce hypertension have been isolated or extracted in water from different basidiomycetes’ edible mushroom fruiting bodies." (PMID 35202112, 2022). "Many elderly patients use ACE inhibitors to treat hypertension and heart failure." (PMID 36016727, 2022). "Angiotensin-I-converting enzyme (ACE) can convert angiotensin I (Ang I) to Ang II for inactivating the vasodilator bradykinin, and ACE inhibitory (ACEi) activity is a vital method for mediating systemic hypertension." (PMID 35323475, 2022). "Therefore, ACE inhibitors are usually preferred antihypertensive drugs in diabetes with hypertension." (PMID 36085061, 2022). "ACE inhibitors and beta-blockers were listed in all NEMLs for the treatment of hypertension." (PMID 36482421, 2022). "Hypertension, duration of diabetes, drinking habit, triglycerides, ACE inhibitors, low-density lipoprotein (LDL) cholesterol, age, and smoking habit were the top-8 features ranked by the XGB model and identified as the most important features for predicting CKD in T1DM patients." (PMID 36143293, 2022). "Therefore, efforts have been made to address plant components such flavonoids, peptides, and phenolic compounds to decrease ACE activity and reduce the high blood pressure." (PMID 36547528, 2022). "We thought this might be related to ACE inhibitors taken by the patients diagnosed with essential hypertension." (PMID 35439945, 2022).